GCNA (germ cell nuclear acidic peptidase)
Description:
May play a role in DNA-protein cross-links (DPCs) clearance through a SUMO-dependent recruitment to sites of DPCs, ensuring the genomic stability by protecting germ cells and early embryos from various sources of damage. Can resolve the topoisomerase II (TOP2A) DPCs (By similarity).
Synonyms: ACRC; NAAR1; SPGFX4
Tractability: No criterion of Open Targets' tractability assessment is met for any kind of drug.
Gene: Protein-coding gene on chromosome X (71,578,437 to 71,613,584, forward strand). Ensembl gene ENSG00000147174.
Subcellular location: Nucleus; Nucleus, PML body; Chromosome
Subcellular location (Human Protein Atlas): Nucleoplasm
Gene Ontology:
Molecular function: protein binding; SUMO polymer binding
Biological process: protein-DNA covalent cross-linking repair; DNA damage response
Cellular component: nucleoplasm; nucleus; PML body; chromosome
Homologues: Orthologues: macaque GCNA (74% identical), chimpanzee GCNA (64% identical), dog GCNA (32% identical), zebrafish gcna (21% identical), Drosophila melanogaster Gcna (16% identical), Caenorhabditis elegans gcna-1 (13% identical), Drosophila melanogaster CG11322 (10% identical), Drosophila melanogaster CG2694 (9% identical).
Diseases named in the same sentence as GCNA in open-access papers:
GCNA is named in the same sentence as 9 diseases in open-access papers, as found by Europe PMC text mining. Sharing a sentence is not in itself a finding about the gene and the disease. The quoted sentences say what the papers report.
Azoospermia (1 paper, 2023). Absence of any measurable level of sperm,whereby spermatozoa cannot be observed even after centrifugation of the semen pellet. "Recently, mutations in GCNA have been linked to azoospermia in humans, defining GCNA as a clinical determinant of human infertility." (PMID 36919611, 2023). "Although mutations in the GCNA locus have been associated with azoospermia in humans, the mechanism behind this is not understood." (PMID 36919611, 2023).
germ cell tumor (1 paper, 2022). A benign or malignant, gonadal or extragonadal neoplasm that originates from germ cells. "In humans, GCNA copy number loss and silencing is particularly evident in pediatric germ cell tumors; tumors with reduced or aboragated GCNA expression show particularly high levels of genome instability." (PMID 35137093, 2022).
tumours (1 paper, 2023). "Although smaller tumours contained some germ cell remnants, more developed tumours did not contain germ cells (GCNA+)." (PMID 37564373, 2023).
GCNA also shares sentences with these, for which no sentence is quoted: cancer (2 papers); gracile bone dysplasia (1); Infertility (1); male infertility (1); mantle cell lymphoma (1); pediatric germ cell tumors (1).